NECTIN4 (nectin cell adhesion molecule 4)
Diseases named in the same sentence as NECTIN4 in open-access papers (continued):
Sharing a sentence is not in itself a finding about the gene and the disease.
follicular thyroid carcinoma (1 paper, 2022). "In contrast, nectin-4 expression was markedly higher in patients with de novo ATC than in those with papillary and follicular thyroid carcinoma." (PMID 35158847, 2022).
gynecologic cancers (1 paper, 2025). "In gynecologic malignancies, we have identified several highly expressed TATs, some of which have been targeted by FDA-approved ADCs, such as TROP2 and Nectin-4, although these drugs have not been approved for the treatment of gynecologic cancers." (PMID 40046734, 2025).
invasive ductal carcinomas (1 paper, 2019). "Whereas 30% of the invasive ductal carcinomas had strong Nectin-4 expression, only 20% of the invasive lobular carcinomas were categorized into this group." (PMID 31572728, 2019).
laryngeal squamous cell carcinoma (1 paper, 2025). A squamous cell carcinoma that arises from the larynx. "The main goal of this pilot study was to evaluate the expression patterns of Nectin-2 and Nectin-4 in laryngeal squamous cell carcinoma (LSCC)." (PMID 40699695, 2025).
lentivirus infection (1 paper, 2022). Virus diseases caused by the Lentivirus genus. "To discuss whether Nectin-4 had an influence on OS cell viability, we firstly constructed and sorted out the OS cell lines with stable Nectin-4 overexpression (Nectin-4-OE) or knockdown by means of lentivirus infection." (PMID 35953862, 2022).
lymphoma (1 paper, 2016). A malignant (clonal) proliferation of B- lymphocytes or T- lymphocytes which involves the lymph nodes, bone marrow and/or extranodal sites. "Finally, the observations that SLAMF1 is found on lymphomas and that Nectin-4 is expressed on the cell surfaces of many adenocarcinomas highlight the potential of measles virus for oncolytic therapy." (PMID 27657109, 2016).
mesothelioma (1 paper, 2017). A usually malignant and aggressive neoplasm of the mesothelium which is often associated with exposure to asbestos. "The incidence of nectin-4 expression in mesothelioma is unknown." (PMID 28968974, 2017). "In the work presented here mesothelioma cells were shown not to be reliant on nectin-4 for viral entry." (PMID 28968974, 2017). "In contrast, mesothelioma cells are not reliant upon the alternative MV-Edm receptor nectin-4 for entry." (PMID 28968974, 2017). "Furthermore, results herein demonstrate that viral entry into mesothelioma cells is dependent upon the expression of CD46 and is independent of nectin-4." (PMID 28968974, 2017).
obstetric disorder (1 paper, 2023). Disorder associated with pregnancy, childbirth, and puerperium. "We previously demonstrated that NECTIN4 is overexpressed in placenta during pre-eclamptic pregnancy, which is one of the most serious obstetric disorders." (PMID 37554937, 2023).
ovarian tumor (1 paper, 2007). "We found that 50% of ovarian tumor cell lines express transmembrane Nectin-4." (PMID 17474988, 2007).
Pan (1 paper, 2024). "In the TCGA Pan-Cancer cohort, NECTIN4 amplifications were observed in 25 of 32 cancer types including various solid entities with NECTIN4 amplification frequency > 5%." (PMID 38657187, 2024).
renal carcinoma (1 paper, 2023). A carcinoma arising from the epithelium of the renal parenchyma or the renal pelvis. "Numerous reports indicate that nectin-4 is overexpressed in a wide array of cancers such as colorectal, gastric, esophageal, breast, ovarian, hepatocellular, non-small-cell lung, urothelial, papillary thyroid, and renal cancers." (PMID 37958883, 2023).
salivary duct carcinoma (1 paper, 2023). An aggressive, high grade adenocarcinoma that arises from the salivary glands. "Additionally, Nectin-4 expression may represent a prognostic factor in salivary duct carcinoma." (PMID 37480387, 2023).
sarcoma (1 paper, 2025). A usually aggressive malignant neoplasm of the soft tissue or bone. "Down-regulation of Nectin4 and B7-H4 was the strongest characteristic of human sarcoma vs all other human cancers." (PMID 40788962, 2025).
sebaceous carcinomas (1 paper, 2024). "For instance, increased nectin-4 expression has been noted in a subset of cutaneous adnexal carcinomas, particularly sebaceous carcinomas, indicating that EV may be a promising treatment for these tumors." (PMID 39712492, 2024).
skin angiosarcoma (1 paper, 2022). A malignant vascular neoplasm arising from the skin. "Of note, positive NECTIN4 cases were more common in tumors with high-grade malignant potential (i.e. non-skin angiosarcoma or epithelioid histopathological subtype), although the correlation was statistically not significant." (PMID 35256687, 2022). "When we analyzed the correlation between NECTIN4 expression and clinical factors, NECTIN4 was frequently positive in tumors with high-grade malignant potential (i.e. non-skin angiosarcoma or epithelioid histopathological subtype), although the correlation was statistically not significant." (PMID 35256687, 2022).
Thrombocytopenia (1 paper, 2024). A reduction in the number of circulating thrombocytes. "However, the binding of Nectin-4 NDC to HSA effectively avoids adverse reactions, such as thrombocytopenia associated with the binding of the Fc domain to Fcγ receptors." (PMID 38755613, 2024).
toxicity (1 paper, 2025). The degree to which an agent can damage an organism. "Similar findings have been described in patients with skin toxicity, which suggests that the efficacy of EV could be related to the amount of MMAE released and, therefore, to nectin-4 expression, also present in the skin." (PMID 41228314, 2025).
tumor (193 papers, 2007 to 2026). "We highlight the rapidly expanding therapeutic roles of ICIs, alongside innovative modalities such as CAR-T cell therapy directed against tumor-associated antigens-including NECTIN4, PSMA, and FRα." (PMID 41919257, 2026). "Nectin-4 expression also aligns with luminal differentiation markers and shows inverse associations with PD-L1 expression on tumour-infiltrating immune cells, suggesting its integration within broader immune-microenvironment contexts." (PMID 41590351, 2026). "In clinical practice, from a cohort of 108 patients with aUC with available tumor tissue samples and treated with EV, NECTIN4 copy number variants were assessed via fluorescence in situ hybridization (FISH)." (PMID 40225697, 2025). "High expressions of Nectin-2 and Nectin-4 have been linked to tumor invasion, angiogenesis, and immune evasion in various epithelial cancers, indicating their potential as markers for tumor aggressiveness and early detection of premalignant lesions." (PMID 40699695, 2025). "The importance of NECTIN4 amplification of the tumor tissue and its association with EV response should be further investigated." (PMID 40225697, 2025). "Only lower tumour stage was associated with significantly higher Nectin‐4 expression (T1 vs ≥pT2; P = 0.005)." (PMID 39801278, 2025). "Similar to TROP‐2, NECTIN‐4 overexpression has been reported in various tumor types, and is linked with several facets of tumor progression, like proliferation, recurrence, and metastasis." (PMID 38895886, 2024). "EV is an ADC consisting of an anti-nectin-4 human IgG1 monoclonal antibody covalently linked to MMAE that exerts its anti-tumor effect by binding to a nectin-4 antibody and being internalized by cells." (PMID 39123376, 2024). "Although the value of Nectin-4 as a diagnostic target has been confirmed in clinical practice, the uptake of 68Ga-N188 in positive tumor lesions was moderate owing to its low affinity." (PMID 38606099, 2024). "Antigen-associated resistance mechanisms include reduced HER2/NECTIN4 levels, tumor heterogeneity, and truncation of the antigen extracellular domain." (PMID 39655080, 2024). "Nectin-4 belongs to a family of cellular adhesion molecules and is found to be overexpressed in various tumours and is associated with cancer progression and poor prognosis." (PMID 38067262, 2023). "This suggests the high sensitivity of scFv L4 binding to native nectin-4 molecule, which supports its potential to be further developed as a tumor-marker-specific diagnostic and/or therapeutic agent." (PMID 38288120, 2023). "High tumor grade and muscle invasiveness (≥T2 tumors) were strongly associated with lower levels of urine Nectin-4 (p < 0.001)." (PMID 37174031, 2023). "A preclinical study suggests tumor Nectin-4 expression is associated with increased EV activity, nominating Nectin-4 as a potential biomarker of response to EV." (PMID 37091148, 2023). "As previously discussed, preclinical models of EV in UC suggest downregulation of Nectin-4 on tumor cells is associated with resistance to therapy." (PMID 36686762, 2022). "The potential mechanism underlying Nectin-4 in promoting the tumor cells growth, proliferation, and movement was confirmed by regulating Ras-related C3 botulinum toxin substrate 1 (Rac1) signaling activity." (PMID 35953862, 2022). "The revealed hyperexpression of nectin-4 by tumor tissues of various malignant neoplasms is associated with tumor aggressiveness and poor clinical prognosis." (PMID 36140182, 2022). "Nectin-4 has been associated with virtually every stage of tumor progression and the dissemination of disease." (PMID 36553083, 2022). "NECTIN4 is overexpressed in many types of human cancers, such as urothelial cancer, and its abnormal expression is associated with tumor progression by increasing proliferation and angiogenesis, and decreasing apoptosis." (PMID 33478111, 2021).
tumor (continued). "Regarding the mechanisms underlying NECTIN4-mediated tumor progression, previous reports demonstrated the involvement of the PI3K/Akt pathway in multiple cancers." (PMID 33478111, 2021). "The most EMPD lesions exhibited strong NECTIN4 expression, and high NECTIN4 expression was significantly associated with increased tumor thickness, advanced TNM stage, and worse disease-specific survival." (PMID 32824340, 2020). "Our results demonstrated that over-expression of Nectin-4 in human EC tissues was significantly associated with tumor size, depth of tumor invasion, and poor prognosis of the EC patients." (PMID 31043861, 2019). "Nectin-4-high expression was also significantly associated with a lower tumor stage (p = 0.025) and pN0 lymph node stage (p = 0.034)." (PMID 31572728, 2019). "Our results demonstrated that over-expression of Nectin-4 in human EC tissues was significantly associated with tumor size, depth of tumor invasion, and poor prognosis of the patients." (PMID 31043861, 2019). "In contrast, NECTIN4 expression showed an association with tumor grade." (PMID 41837391, 2026). "Interestingly, high Nectin‐4 expression in the LNs was significantly associated with the presence of lymphovascular invasion in primary tumours (P = 0.038)." (PMID 39801278, 2025). "Moreover, elevated NECTIN-4 RNA expression correlates with a high tumor mutation burden, reduced PD-L1 expression, and lower immune cell fractions." (PMID 39941802, 2025). "Given the importance of nectin-4 in tumor initiation and progression, antibodies against nectin-4 could be a helpful diagnostic/therapeutic tool." (PMID 38288120, 2023). "The Nectin-4 high expression was strongly associated with tumor metastasis (P < 0.05)." (PMID 35953862, 2022). "In addition, we also found that the Nectin-4 high expression was markedly associated with tumor metastases in GSE21257." (PMID 35953862, 2022). "Due to the fact that Nectin-4 is mainly expressed during fetal development with a decrease of expression in adult tissues, its re-expression during tumor development makes it a tumor-associated antigen with the possibility of developing a targeted therapy." (PMID 31572728, 2019). "It was also demonstrated that the ectodomain shedding of transmembrane glycoproteins such as nectin-1 or nectin-4 by matrix metalloproteases (MMPs) or ADAMs (a disintegrin and metalloproteinases) causes a decrease in cell-cell interaction and is involved in tumor cell migration and invasion." (PMID 31419250, 2019). "Nectin-2 and Nectin-4 are often overexpressed in tumours, and are associated with a poor prognosis." (PMID 24386110, 2013). "Thus, Nectin-4 is a new tumor-associated antigen and is a candidate for passive and active immunotherapy." (PMID 17474988, 2007). "We hypothesized that this analysis would enhance the knowledge about Nectin-2 and Nectin-4 regarding their potential function as novel biomarkers associated with tumor aggressiveness and metastatic potential in LSCC, contributing to risk stratification and therapeutic decision-making." (PMID 40699695, 2025). "Furthermore, in our cohort, high Nectin‐4 expression was significantly associated with lower tumour stage, which is in accordance with a former study that found higher Nectin‐4 expression levels in NMIBC samples (with 87% staining positivity) than in MIBC samples (with only 58% staining positivity)." (PMID 39801278, 2025). "First, many tumor antigens are also expressed in normal tissues to varying degrees, leading to the possibility of off-target toxicity in normal tissues while attacking tumor cells, e.g., the expression of NECTIN-4 in skin tissues explains ADC-associated rashes and itchy side effects." (PMID 40433388, 2025). "Nectin-4–targeted imaging also addresses the challenge of tumor heterogeneity in UC, where variable Nectin-4 expression affects therapeutic outcomes." (PMID 41499516, 2026).
tumor (continued). "Because it is expressed in several other tumour entities, such as breast cancer, gastrointestinal tumours and lung cancer, Nectin‐4 is one of the most promising pan cancer targets." (PMID 40847665, 2026). "A retrospective cohort study reported that 39% of metastatic lesions showed decreased Nectin‐4 compared to the primary tumor, which correlated with reduced EV efficacy." (PMID 41403786, 2026). "Nectin‐4 PET is suitable for detecting Nectin‐4 expression in tumour lesions and demonstrates heterogeneity in Nectin‐4 expression – for example, between lymph node metastases and organ metastases." (PMID 40847665, 2026). "have shown by IHC and molecular analysis that, in patients receiving enfortumab monotherapy, high Nectin‐4 expression levels in tumour tissue correlate with improved survival." (PMID 40847665, 2026). "EV binds Nectin‐4, internalizes, and releases monomethyl auristatin E (MMAE) causing tumor necrosis." (PMID 41472900, 2026). "Independent studies have found that greater Nectin-4 expression correlates with papillary morphology, lower tumour grade, and earlier pathological stage, with more favourable outcomes associated with predominantly membranous staining." (PMID 41590351, 2026). "Recently, a QuPath-based ML workflow using a Random Trees classifier for tumour-cell classification and automated H-score computation was applied to quantify Nectin-4 intensity and assess spatial distribution and prognostic correlations in MIBC." (PMID 41590351, 2026). "It binds several nectin/nectin-like ligands, including PVR (CD155), PVRL2 (CD112), PVRL3 (Nectin-3, CD113), and PVRL4 (Nectin-4), all commonly expressed by tumor cells and APCs." (PMID 41486149, 2026). "PET imaging identified dose-dependent variations in Nectin-4 engagement, with suboptimal EV doses resulting in incomplete Nectin-4 engagement and increased tumor growth." (PMID 41499516, 2026). "Immunohistochemistry showed a marked decline in Nectin‐4 expression in the resected tumor compared with at the time of the initial biopsy." (PMID 41403786, 2026). "Nectin-4 displayed strong heterogeneous cytoplasmic staining and focally strong membranous staining in specific tumor areas." (PMID 40699695, 2025). "The evolution of ADC target selection has progressed from hematologic-specific CD antigens (e.g., CD30, CD22, CD33, CD79b) to tumor-associated antigens more commonly expressed in solid tumors, such as HER2, TROP2, Nectin-4, and folate receptor α." (PMID 41184856, 2025). "For matched TC region vs corresponding LN analysis of Nectin‐4 expression levels, 51 sample pairs were available for direct comparison between the primary tumours and positive LNs." (PMID 39801278, 2025). "Collectively, these findings demonstrate that rosiglitazone increases NECTIN4 expression in multiple UC tumor xenografts." (PMID 40931013, 2025). "We evaluated the association between Nectin‐4 and ABC transporter expression in primary tumour samples, including both non‐muscle‐invasive and muscle‐invasive tumours, and PFS after EV therapy in all 20 patients." (PMID 39877564, 2025). "Enhanced staining at the invasive tumor margins was observed for both Nectin-2 and Nectin-4, with a more pronounced pattern for Nectin-4, suggesting involvement of this molecule in tumor invasiveness and progression." (PMID 40699695, 2025). "Thepresent study aimed at translating the nectin-4-directed bicyclictoxin conjugate BT8009 into radiolabeled bicyclic peptidesfor noninvasive tumor imaging with positron emission tomography." (PMID 41081542, 2025). "The IHC staining results for Nectin-2 and Nectin-4 in LSCC confirmed the expression of both molecules in the tumor parenchyma and the surrounding stroma." (PMID 40699695, 2025). "In the present study, we examined – for the first time – the spatial heterogeneity of membranous Nectin‐4 expression within primary UBCs and between primary tumours and positive LNs." (PMID 39801278, 2025).